RUNX3 (RUNX family transcription factor 3)
Diseases named in the same sentence as RUNX3 in open-access papers (continued):
Sharing a sentence is not in itself a finding about the gene and the disease.
neuroblastoma (continued). "In summary, considering an increase in TrkA and TrkC expression is associated with favorable biological features in neuroblastoma, RUNX3 may simply be categorized as a functional tumor suppressor in neuroblastoma because of its potential to positively regulate TrkA and TrkC." (PMID 36831211, 2023). "Based on a study using neuroblastoma-derived cell lines, even the transactivation deficient mutant form of RUNX3 promotes ubiquitination and protein degradation of MYCN, suggesting that RUNX3 might recruit an E3 ubiquitin ligase of MYCN in a transactivation-independent manner." (PMID 36831211, 2023). "In conclusion, the present study demonstrates that, by activating epigenetic mechanisms involving derepression of RUNX3 expression and stimulating signaling pathways mediated by ERK1/2 and JNK, VPA upregulates TrkC in human neuroblastoma cells." (PMID 34360553, 2021). "It has been reported that high EZH2 expression is prognostic for poor clinical outcome in neuroblastoma patients and that EZH2-catalyzed H3K27me3 is responsible for transcriptional repression of several neuroblastoma tumor-suppressor genes, including CASZ1 GLU, RUNX3, and NGFR19." (PMID 30631055, 2019). "Therefore, in contrast to RUNX3, RUNX1, together with the RUNX1-mediated decrease in TrkA and TrkC, may be essential for neuroblastoma proliferation, especially in neuroblastomas with the 1p36 deletion." (PMID 36831211, 2023).
prostate carcinoma (9 papers, 2009 to 2024). A carcinoma that arises from epithelial cells of the prostate gland. "We found that loss of RUNX3 expression directly correlated with prostate cancer TNM stage." (PMID 24475196, 2014). "However, the molecular basis of loss or decrease of RUNX3 expression in prostate cancer still remains to be determined." (PMID 24475196, 2014). "RUNX3 overexpression in prostate cancer cells showed inhibition in cell migration and invasion with an upregulation of tissue inhibitor of matrix metalloproteinase-2 (TIMP-2)." (PMID 33298014, 2020). "Altogether, our results support the tumor suppressive role of RUNX3 in human prostate cancer, and provide insights into development of targeted therapy for this disease." (PMID 24475196, 2014). "In this study, we examined the expression of RUNX3 in relation to clinicopathologic features using prostate cancer tissue microarray." (PMID 24475196, 2014). "In this study, we found that forced RUNX3 expression significantly inhibited prostate cancer cell migration and invasion abilities." (PMID 24475196, 2014). "We first examine the effect of RUNX3 reintroduction on prostate cancer cells migration and invasion." (PMID 24475196, 2014). "Our in vitro studies revealed that RUNX3 in prostate cancer cells reduces cell migration, invasion and angiogenesis abilities, which was consistent with the function of RUNX3 in vivo." (PMID 24475196, 2014). "In conclusion, this study provides evidence that decreased RUNX3 expression is significantly correlated with TNM stage of patients with prostate cancer." (PMID 24475196, 2014). "Our results showed ectopic expression of RUNX3 in prostate cancer tissues when compared with tumor adjacent normal prostate tissues, and reduced RUNX3 staining was significantly correlated with TNM stage." (PMID 24475196, 2014). "In the current study, we found that restoration of RUNX3 in prostate cancer cells simultaneously up-regulated TIMP-2 expression, which is the negative regulator of MMP-2." (PMID 24475196, 2014). "Our clinical evidence clearly supported the notion that altered expression of RUNX3 contributes to prostate cancer development and metastasis." (PMID 24475196, 2014). "Better to understand the exact role of RUNX3 in prostate cancer development, we used TMA technology, in vitro cell model and in vivo animal model to investigate the role of RUNX3 in prostate cancer." (PMID 24475196, 2014). "In this study, we used tissue microarray (TMA) to determine the significance of RUNX3 in prostate cancer progession." (PMID 24475196, 2014). "In prostate cancer, reduced levels of RUNX3 have been correlated with tumor stage and grade." (PMID 33298014, 2020). "In this study, we found that RUNX3 expression was lost in prostate cancer tissue." (PMID 24475196, 2014). "Our data showed that VEGF secretion was decreased by restoration of RUNX3 in prostate cancer cells." (PMID 24475196, 2014). "Furthermore, we demonstrated that decrease of VEGF secretion induced by RUNX3 reintroduction inhibited prostate cancer angiogenesis." (PMID 24475196, 2014). "Since RUNX3 expression is related to TNM stage with prostate cancer, RUNX3 may play important roles in one or more steps of prostate cancer metastasis." (PMID 24475196, 2014). "Furthermore, Overexpression of RUNX3 suppressed DU145 distant lung metastasis in nude mouse model, which suggested the tumor suppressor role of RUNX3 in prostate cancer metastasis." (PMID 24475196, 2014). "Furthermore, the inhibition of VEGF after RUNX3 restoration greatly contributed to tumor angiogenesis of prostate cancer cells in vitro and vivo." (PMID 24475196, 2014). "Our clinical and mechanistic data indicated that RUNX3 may be a tumor suppressor involved in the progression of prostate cancer and targeting of RUNX3 pathway constituted a potential treatment modality for human prostate cancer." (PMID 24475196, 2014). "RUNX3 suppresses prostate cancer metastasis due to the imbalance between MMP-2 and TIMP-2." (PMID 24475196, 2014).
prostate carcinoma (continued). "Our clinical results showed that RUNX3 was lost in prostate cancer and correlated with TNM stage." (PMID 24475196, 2014). "Indeed, we also found that most of the top ten methylated genes were completely silenced in all the three cell lines, including RUNX3, whose promoter has been found previously to be DNA hypermethylated in prostate cancer patients." (PMID 21108828, 2010). "We first determined whether RUNX3 expression is changed in human prostate cancer." (PMID 24475196, 2014). "Moreover, we demonstrated that RUNX3 overexpression inhibited prostate cancer cell migration and invasion resulting from the elevated upregulation of tissue inhibitor of matrix metalloproteinase-2 (TIMP-2), which subsequently inhibited metalloproteinase-2 (MMP-2) expression and activity in vitro." (PMID 24475196, 2014). "The number of VIII-positive microvessels was much lower in the sections from xenografts of RUNX3-expressing DU145 cells, indicating that RUNX3 attenuated prostate cancer cell-inducing angiogenesis." (PMID 24475196, 2014). "Because TNM stage is an important prognostic marker for patients with prostate cancer, we detected the RUNX3 expression in 139 early-stage (I–II) and in 79 late-stage (III–IV) categories of prostate cancer tissues." (PMID 24475196, 2014). "We also found >2 fold signal in genes previously identified as methylated in prostate cancer such as CDKN2A (average of 15.8 fold enrichment), RUNX3 (2.8 fold), and PTGS2 (2.9 fold)." (PMID 19283074, 2009). "These suggested that RUNX3 was commonly expressed in normal human prostate tissue but decreased or absent in prostate cancer tissue." (PMID 24475196, 2014). "There has been evidence that RUNX3 methylation was especially frequent in different cohorts of prostate cancers but not in normal prostate mucosa." (PMID 24475196, 2014). "In the present study, we noticed that RUNX3 regulated prostate cancer cell metastasis through MMP-2 but not MMP-9." (PMID 24475196, 2014). "The functional role exhibited by RUNX3 is very similar to the role CD82 plays in prostate cells, i.e., CD82 reexpression has been shown to inhibit EMT, inhibit migration and invasion and its down-regulation has been correlated with poor prognosis in prostate cancer." (PMID 33298014, 2020). "However, the function of RUNX3 in prostate cancer has not been examined." (PMID 24475196, 2014). "However, the function of RUNX3 in prostate cancer has not yet been well studied." (PMID 24475196, 2014).
colitis (8 papers, 2016 to 2023). Inflammation of the colon. "Runx3 deficiency in murine hematopoietic cells has been linked to the development of various autoimmune diseases, such as colitis and airway hypersensitivity." (PMID 36231078, 2022). "Mice deficient in the transcription factor Runx3 develop a multitude of immune system defects, including early onset colitis." (PMID 32453801, 2020). "Among three mammal Runx proteins Runx1, Runx2, and Runx3, loss of Runx3 in hematopoietic cells leads to spontaneous development of colitis and airway infiltration in part by altering DCs function." (PMID 31818882, 2020). "It should also be emphasized that while Runx3 and Il10r deficiencies in RM lead to colitis, each model bears unique features." (PMID 32453801, 2020). "The fact that Runx3 is not expressed in normal colonic epithelium, suggests that loss of a leukocytic cell-autonomous Runx3 function was the driving force of colitis development in these mice." (PMID 32453801, 2020). "Furthermore, these studies have used murine colitis models to demonstrate the detrimental loss of RUNX3 in intestinal CD4+ T cells in driving their Th17 polarization and promoting chronic inflammation." (PMID 36231078, 2022). "Runx3 deletion in MNP causes early onset colitis due to their impaired maturation." (PMID 32453801, 2020). "As loss of Runx3 in MNP triggers spontaneous colitis, we sought to determine whether alterations in the colonic MNP compartment of Runx3Δ mice precede the onset of colitis." (PMID 32453801, 2020). "In view of the defects in different cell types of innate and adaptive immune systems in Runx3-/- mice, and the association of RUNX3 with immune-related human diseases, we sought to determine which of the Runx3-/- immune cell types is directly involved in colitis development." (PMID 32453801, 2020). "Strikingly, the majority of ~3-month-old mice of both MNP-specific Runx3-cKO models spontaneously developed mild colitis that affected the cecum and proximal colon." (PMID 32453801, 2020). "Taken together, our results suggest that Runx3-/- CD11b+ MNPs, including RM and CD11b+ DC, drive the spontaneous development of colitis in Runx3-/- mice." (PMID 32453801, 2020). "To establish whether Runx3-/- leukocytes are involved in colitis development, we performed a transfer experiment." (PMID 32453801, 2020). "Therefore, the similar spontaneous colitis phenotype in these three strains cannot be explained by cross-regulation between Runx3 and signals emanating from the Il10 receptors." (PMID 32453801, 2020). "The loss of Runx3 in MNP results in a decreased abundance of colonic P3-P4 mature anti-inflammatory RM and CD103+CD11b+ cDC2, which occurs prior to the onset of significant colitis symptoms, suggesting that these changes are indeed the cause of colitis." (PMID 32453801, 2020). "It was reported that Runx3 loss in hematopoietic cells and loss of CD103+CD11b+ cDC2s by lack of TGFβ receptor signaling resulted in spontaneous colitis development." (PMID 31818882, 2020). "Thus, Runx3 function in normal RM to repress pro-inflammatory genes and induce anti-inflammatory genes, is consistent with its ability to protect against colitis." (PMID 32453801, 2020). "Previously we reported that Runx3-/- mice develop early onset spontaneous colitis." (PMID 32453801, 2020). "Colitis in these Runx3-cKO mice displayed similar characteristics to those observed at an earlier age in Runx3-/- mice, including accumulation of infiltrating leukocytes associated with pronounced mucosal hyperplasia and loss of differentiated mucous secreting goblet cells." (PMID 32453801, 2020). "Furthermore, Runx3-/- mice spontaneously develop colitis at 4–6 weeks of age." (PMID 32453801, 2020). "As colitis developed in the MNP-specific Runx3-cKO mice, we determined which subtype of colonic lamina propria (LP) MNP cells expresses Runx3 by employing Runx3-GFP compound heterozygous mice described previously." (PMID 32453801, 2020).
colitis (continued). "The observations presented above revealed that while colonic RM and CD11b+ DC are formed in the absence of Runx3, Runx3Δ mice can still develop colitis." (PMID 32453801, 2020). "Unlike the spontaneous colitis seen in Runx3-/- mice, Lck-Runx3Δ mice did not develop spontaneous colitis." (PMID 32453801, 2020). "Here, we provide direct evidence that transfer of Runx3-/-, but not WT, FL, or BM cells into lethally irradiated mice induced colitis in the recipient mice." (PMID 32453801, 2020). "Here, we show that conditional deletion of Runx3 specifically in MNP, but not in T cells, recapitulates the spontaneous colitis seen in Runx3-/- mice." (PMID 32453801, 2020). "Previous research has shown that conditional deletion of Runx3 in NK cells and ILCs by crossing Runx3fl/fl mice on to Nkp46-Cre mice does not induce spontaneous colitis, although those mice did show more severe intestinal damage following infection with Citrobacter rodentium." (PMID 32453801, 2020). "The methylation level of RUNX3 P2 did not correlate with age, sex, nutritional status, CRP, albumin, PUCAI, or the extent of colitis (Paris E1–E4)." (PMID 36140736, 2022). "Moreover, conditional deletion of Runx3 in MNP, but not in lymphocytes, recapitulated the spontaneous development of colitis observed in Runx3-/- mice." (PMID 32453801, 2020).
glioblastoma (8 papers, 2016 to 2025). The most malignant astrocytic tumor (WHO grade IV). "RUNX3 gene is located in 1p36, a region of frequently genomic loss in a wide variety of human carcinomas, including glioblastoma." (PMID 29340016, 2017). "By catalyzing H3K27me3, EZH2 represses a series of tumor suppressor genes associated with the tumorigenic properties of glioblastoma, including CDKN1B, RUNX3, and HOXA5." (PMID 35927718, 2022). "Since protein expression of RUNX3 is decreased in glioblastomas compared to lower-grade astrocytoma tumours we performed U87-MG cells proliferation analysis after RUNX3 reexpression." (PMID 31467531, 2019). "Hypermethylation of RUNX3 promoter was also observed in glioblastoma cell lines and primary tumour tissue compared to normal human brain tissue." (PMID 31467531, 2019). "The highest RUNX3 methylation frequency was observed in glioblastoma tissue specimens and even 34 out of 49 samples were methylated (69.4%)." (PMID 31467531, 2019). "Functional study of RUNX3 revealed that reexpression of RUNX3 weighty reduces U87-MG glioblastoma cell viability indicating oncosupressive features of RUNX3." (PMID 31467531, 2019). "We found that RUNX3 protein expression is reduced in glioblastomas as compared to grade II-III tumours and this reduction is associated with patient overall survival." (PMID 31467531, 2019). "RUNX3 was reported to be downexpressed primary glioblastomas, and its overexpression resulted in significantly repressed cell invasion and migration abilities." (PMID 29340016, 2017). "miR‐148‐3p is primarily involved in glioblastoma multiforme (GBM) through its direct regulatory effects on DNMT1 and recombinant human runt‐related transcription factor 3 (RUNX3)." (PMID 40387409, 2025).
inflammatory bowel disease (8 papers, 2013 to 2023). A spectrum of small and large bowel inflammatory diseases of unknown etiology. "Runt-related transcription factor 3 (RUNX3) reveals functional duality in the pathogenesis of inflammatory bowel disease." (PMID 36140736, 2022). "RUNX3 knockout mice spontaneously develop inflammatory bowel disease characterized by leukocyte infiltration, mucosal hyperplasia, formation of lymphoid clusters, and increased production of IgA." (PMID 23637848, 2013). "Besides, Runx3 knockout mice spontaneously develop inflammatory bowel disease with enhanced expression of both Th1 and Th2 signature cytokines." (PMID 35844683, 2021). "Furthermore, data from inflammatory bowel disease and preclinical models suggest that RUNX3 induced polarization of CD4+ cells towards a CD4+ CTL phenotype may be especially important in the gut epithelium." (PMID 36900240, 2023). "These included elevated methylation levels in CpG islands associated with FZD1 and RUNX3, both of which encode proteins that regulate ovarian folliculogenesis, and also RASAL3, which controls a magnitude of inflammatory responses and has been linked specifically to inflammatory bowel disease." (PMID 34996447, 2022). "Histopathological analysis performed 2 months after transfer revealed that recipients of Runx3-/-, but not of WT FL cells, developed inflammatory bowel disease (IBD)." (PMID 32453801, 2020).
systemic lupus erythematosus (8 papers, 2015 to 2026). An autoimmune multi-organ disease typically associated with vasculopathy and autoantibody production. "We find suggestive, under-characterized TFs, such as RUNX3 in mesoderm development and GLI1 in systemic lupus erythematosus." (PMID 36040971, 2022). "On the other hand, NETosis in systemic lupus erythematosus (SLE), inhibition of TGF-β1 signaling, IL-1 signaling, transcription androgen receptor nuclear signaling, and inhibition of RUNX3 signaling were the main enriched pathways in Th2-enriched CD4+ T cells from peripheral blood in AR patients." (PMID 35246242, 2022).
triple-negative breast carcinoma (8 papers, 2019 to 2026). An invasive breast carcinoma which is negative for expression of estrogen receptor (ER), progesterone receptor (PR), and human epidermal growth factor receptor 2 (HER2). "In particular, miR-20a-5p is highly expressed in tissues and cell lines of triple-negative breast cancer, where it promotes triple-negative breast cancer cell growth by targeting the Runt-related transcription factor 3 (RUNX3)." (PMID 41362671, 2026). "miR-20a-5p was identified to be highly expressed in triple-negative breast cancer (TNBC) tissues, which promoted TNBC progression by targeting Runt-related transcription factor 3 (RUNX3)." (PMID 32793474, 2020). "MiR-20a-5p was highly expressed in both triple-negative breast cancer (TNBC) tissues and cell lines, and promoted the growth of TNBC cells through targeting Runt-related transcription factor 3 (RUNX3)." (PMID 31196157, 2019).
breast tumor (7 papers, 2008 to 2023). "Additionally, RUNX3 was shown to negatively regulate genes associated with infiltration of immune cells into the breast tumor microenvironment and with poor prognosis." (PMID 36831308, 2023). "mRNA upregulation of RUNX3 has been noted in primary breast tumor samples through whole genome sequencing analysis." (PMID 36831308, 2023). "According to the known biological observations, the most significant change occurs in the expression of DNMT1 and RUNX3 in different types of malignancies including breast tumor." (PMID 35898303, 2022). "A recent report found that RUNX3 binds to the promoter of FOXP3 and increases Treg population in the tumor microenvironment, which is associated with the progression of breast tumors." (PMID 31075939, 2019). "RUNX3 is an established breast tumor suppressor, and it has been demonstrated that its down-regulation is controlled by H3K27me3 through EZH238." (PMID 26868841, 2016). "Data obtained with an experimentally generated CAF line suggest that increased RUNX3 expression could contribute to the tumor‐promoting ability of CAFs through mediating cancer cell growth and neoangiogenesis in human breast tumors." (PMID 37641472, 2023). "The immune suppressive role of RUNX3 has been reported in breast tumors via regulation of Tregs." (PMID 31075939, 2019). "Recently, such gradient was also detected for RUNX3 methylation, which together with RASSF1A methylation is among the earliest carcinogenetic events in breast tumor transformation." (PMID 18990230, 2008).